TNF (tumor necrosis factor)
Diseases named in the same sentence as TNF in open-access papers (continued):
Sharing a sentence is not in itself a finding about the gene and the disease.
tumor (continued). "In the TME of a tumor, TNF-α plays a complex dual role, both as an inhibitor of tumorigenesis and, under certain conditions, as a potential promoter of tumor progression." (PMID 41376630, 2025). "In an orthotopic OS mouse model, we show that labeled M1-MVs selectively localize to the tumor xenograft and effectively increase the M1/M2 macrophage ratio within the tumor microenvironment, along with elevated plasma TNF-α levels." (PMID 41148831, 2025). "Platelet interactions with monocytes can induce the release of inflammatory cytokines such as tumor necrosis factor α (TNFα), interleukin (IL)-1β, IL-6, and IL-8, which reinforce the inflammatory tumor microenvironment." (PMID 40538536, 2025). "In mice, exogenous TNF injection enhanced tumor growth in the lung through the expansion of pulmonary Treg via the interaction with TNFR2." (PMID 40977146, 2025). "M1 macrophages, often referred to as “classically activated” macrophages, produce pro-inflammatory cytokines such as TNF-α, IL-1β, and IL-6, as well as nitric oxide (NO), and exhibit strong anti-tumor activity." (PMID 40328748, 2025). "Blocking the PD-1 signal restores cytokine release (IFN-γ, Tumor Necrosis Factor (TNF), Interleukin 2) and preserves a pool of memory T-cells that sustains long-term tumor control." (PMID 40725844, 2025). "The administration of recombinant TNFα shows powerful anti-tumor activity in vivo, but early-stage clinical trials were hampered by severe toxicities." (PMID 40649953, 2025). "By producing mediators such as chondroitin sulfate, TNF, IL-1, and IL-6, it increases inflammatory response and induces apoptosis in tumor cells." (PMID 40244052, 2025). "Sustained inflammatory responses, mediated by immune cells and key pro-inflammatory cytokines such as TNF-α, IL-6, and IL-1β, play a pivotal role in shaping the tumor immune microenvironment (TME) and facilitating cancer progression." (PMID 41009721, 2025). "TNFα, while capable of inducing apoptosis in some contexts, often promotes tumor growth in prostate cancer by sustaining chronic inflammation and fostering a tumor‐friendly microenvironment." (PMID 40444484, 2025). "The identification of TNF-α signaling as an early EMT event further underscores the complexity of ECM-mediated signaling in tumor progression." (PMID 40954257, 2025). "In conjunction with other cytokines such as TNF-α and IL-6, this forms a critical axis impacting ferroptosis in inflammatory and tumor immune environments." (PMID 40547014, 2025). "Compared with other treatments, combination therapy with ICAM‐1–Dxd and B7‐H3‐CD3 significantly elevated the concentrations of tumor‐suppressive cytokines, including TNF‐α, IL‐6, and IFN‐γ, to a greater extent." (PMID 39996528, 2025). "In order to examine macrophage-tumor cell crosstalk in PDAC, we categorized patient tumor samples based on macrophage abundance and TNF expression." (PMID 40634284, 2025). "We found that CD4+ T, CD8+ T, proliferating T cells (T-pro), and NK cells activated the anti-tumor function of TANs through TNF and IFNG, including cytotoxicity, cytokine production, chemotaxis, migration and IFNγ signaling." (PMID 40360503, 2025). "Receiver Operating Characteristic (ROC) analysis indicated that TNF-α, IL-6 and IL-12 had the strongest ability to discriminate tumour from normal tissue and provided data-driven cut-offs for subsequent analyses." (PMID 41465261, 2025). "N1-TANs (CD16+) exhibit pronounced antitumour activity, releasing ROS and TNF-α to directly kill tumour cells, whereas also promoting T-cell responses through antigen presentation." (PMID 41451221, 2025). "Compared with TNFRSF18+ T cells, TNFRSF18− T cells exhibited stronger cytotoxic activity against tumour cells within the TNF signalling pathway." (PMID 40770837, 2025). "The results confirmed that APS inhibited tumour growth by modulating the immune function, as evidenced by the increased thymus and spleen indices and elevated levels of IL-2, IL-12, and TNF-α." (PMID 40649307, 2025).
tumor (continued). "Inflammatory molecules such as IL-6, TNF-α, and IL-1β send signals that help tumor cells take in more glucose, produce more fats, and change how they use oxygen for energy." (PMID 41514860, 2025). "NF-κB-induced inflammatory cytokines, such as TNF-α, IL-1β, and IL-6, promote infiltration of tumor infiltrating macrophages (TAMs) and neutrophils into the tumor microenvironment, inhibiting cytotoxic T cell functions." (PMID 40169858, 2025). "Silences tumor suppressor pathways (drives inflammation through cytokines such as TNF-α and CXCL9), promotes epithelial-mesenchymal transition." (PMID 39973938, 2025). "Studies have shown that EVs anchored with superparamagnetic iron oxide nanoparticles and tumor necrosis factor can both enable tumor targeting under the action of external magnetic fields and inhibit tumor growth." (PMID 40804047, 2025). "The elevated level of TNF-α in rat serum can improve the body’s immune function, which in turn inhibits tumor growth and exerts its anti-tumor effect." (PMID 40230723, 2025). "These OVA-decorated AuNPs inhibited tumor growth by inducing higher levels of inflammatory factors (IL-1β, IL-6, and TNF-α) by activated macrophages." (PMID 40801739, 2025). "Concurrently, triggering the release of proinflammatory cytokines such as tumor necrosis factor‐alpha (TNF‐α) and IL‐6, promoting the phagocytosis and subsequent elimination of tumor cells." (PMID 40900811, 2025). "M1 macrophages primarily target tumor cells through the release of cytokines (such as TNF-α) and phagocytosis, playing a role in promoting inflammation." (PMID 40704062, 2025). "The TNF signaling pathway plays a dual role in immune response and tumorigenesis, as it can both promote tumor initiation and potentially inhibit tumor growth." (PMID 40141200, 2025). "During this process, drug-resistant stem/progenitor-like epithelial populations can stimulate myCAFs to produce CCL2 via soluble mediators (e.g., TNF), thereby recruiting CCR2+ tumor-associated macrophages (TAMs)." (PMID 41514658, 2025). "Despite promising preclinical findings, clinical application faces challenges due to the dual role of TNF-α in both promoting and inhibiting tumor progression." (PMID 40558596, 2025). "The DNA aptamer specific to PD-L1, aptPD-L1, stimulated IFN-γ, IL-2, C-X-C motif chemokines, TNF-α, proliferation of cytotoxic and helper T cells infiltrated in tumours and also inhibited in vivo tumour growth." (PMID 41012445, 2025). "M1 macrophages secrete inflammatory cytokines, such as TNF-α, which promote Th1 responses that enhance resistance against tumor growth." (PMID 40648713, 2025). "Under depressive conditions, elevated levels of TNF-α facilitate tumor cell growth and survival through activation of the PI3K–AKT signaling pathway." (PMID 41000397, 2025). "Glycolysis provides the necessary energy for the production of proinflammatory cytokines, such as tumor necrosis factor-alpha (TNF-α) and interleukin-1β (IL-1β), which help activate other immune cells and promote tumor cell elimination." (PMID 40563466, 2025). "The latest reports confirmed that inhibition of Glut1 genetically and pharmacologically sensitises tumours to antitumour immunity and synergises with anti‐PD‐1 therapy through the TNF‐a pathway." (PMID 39754316, 2025). "Paradoxically named for its anti-tumor effects in certain contexts, chronic TNF-α exposure actually tends to promote tumor progression by sustaining inflammation and activating survival pathways." (PMID 41007766, 2025). "TNF-α, a critical inflammatory mediator, can induce cell death in tumor cells but generally has less toxicity to normal cells." (PMID 40365317, 2025). "MSCs in the tumor microenvironment by pro-inflammatory cytokines IFN-γ, TNF-α, or IL-1β can be activated and secreted by macrophages and tumor cells." (PMID 39974358, 2025).
tumor (continued). "MC degranulation can impair regulatory T cell activity and promote cytotoxic T lymphocyte (CTL)–mediated tumor cell killing through tumor necrosis factor α (TNF-α) release." (PMID 41567205, 2025). "TNFα can directly influence the transition of macrophages to the M1 phenotype, typically exhibiting tumor-suppressive properties." (PMID 40869207, 2025). "Increased levels of cytokines such as interleukin-6 (IL-6) and tumor necrosis factor-alpha (TNF-α) are observed in HPV-associated cancers, aiding in tumor growth, angiogenesis, and metastasis." (PMID 40006976, 2025). "By targeting TAK1-mediated survival signaling, DHC not only sensitizes tumor cells to TNF-α but also potentiates cell cycle arrest and apoptotic responses." (PMID 40507823, 2025). "Research indicates that mast cells in gastric cancer can suppress T cell proliferation through the TNF-α-PD-L1 axis, thereby facilitating tumor growth." (PMID 39814702, 2025). "PD-1 signaling is conventionally recognized to suppress IFN-γ, TNF-α, Perforin, and Granzyme B in tumor-infiltrating T cells." (PMID 40825269, 2025). "Non‐stressed tumour‐bearing mice displayed higher levels of TNFα in the prefrontal cortex (PFC) compared to stressed mice with cancer." (PMID 40172096, 2025). "M1 macrophages participate in anti-tumor immune responses by secreting pro-inflammatory cytokines, such as tumor necrosis factor-alpha (TNF-α), and inducible nitric oxide synthase (iNOS)." (PMID 41306968, 2025). "Non-canonical CD8+ T-cell subpopulation producing IL-17A (Tc17) accelerates tumor growth via IL-17RA-dependent stroma modification, as IL-17A and TNF synergistically induce differentiation of inflammatory CAFs (iCAFs) by IL-17RA." (PMID 40427098, 2025). "CD8+ T cell cytotoxicity, as defined by the ability to produce IFN-γ and TNF-α, were also similar between the two tumor types." (PMID 40553564, 2025). "Our results collectively demonstrate that compromising TAK1 function within tumor cells leverages the cytotoxic capacity of TNF to enhance anti-tumor immunity and generate deeper and more durable anti-tumor immune responses in preclinical models of cancer." (PMID 41102176, 2025). "Targeting specific cytokines produced by tumor cells (e.g., IL-6, TNF-α) to modulate immune cells in the TME has shown potential efficacy in clinical trials." (PMID 40092993, 2025). "Research indicates that TNF-α is crucial for processes of tumor proliferation, migration, invasion, and angiogenesis." (PMID 41011149, 2025). "Consistently, TNF signalling emerged as the dominant pathway mediating tumour cell‐immune cell crosstalk, particularly between tumour cells and T cells." (PMID 40770837, 2025). "Consistent results were achieved for all 94 paired tumour–normal samples for TNF-α and IFN-γ, for 93 paired samples for TGF-β1 and IL-1α, for 90 paired samples for IL-1β and IL-12, and for 87 paired samples for IL-2 and IL-6 expression." (PMID 41465261, 2025). "Here, we determined the levels of three relevant cytokines involved in tumor progression: (a) IL-2, (b) IL-6, and (c) TNF-α." (PMID 41155954, 2025). "γδ2+ T cells exert antitumor effects through production of cytokines like IFN-γ and TNF-α and direct tumor cell lysis." (PMID 40236336, 2025). "Beyond direct antiviral activity, alloferon exhibits tumor-suppressive effects via NK cell-mediated immunomodulation, characterized by elevated IFN-γ and TNF-α secretion within tumor niches." (PMID 40507941, 2025). "TAMs have been shown to induce EMT of tumor cells by secreting cytokines such as TNF‐α and transforming growth factor (TGF)‐β in the TME in various cancers." (PMID 40257446, 2025). "Overexpression of TNFα can fragment tumor DNA, thereby contributing to resistance to the cytotoxic effects of chemotherapeutic agents." (PMID 41035952, 2025). "AKBA also inhibits tumor cells by reducing the NF-κB signaling pathway, which reduces TNF-α production and prevents further inflammation." (PMID 40746878, 2025).
tumor (continued). "M1 macrophages can secrete pro-inflammatory molecules such as IL-1, IL-18, and TNF-α, which exert anti-tumor effects." (PMID 40704015, 2025). "Pro-inflammatory mediators such as TNF-α, IL-1β, and IL-6 not only stimulate angiogenesis but also alter tumor cell adhesion and infiltration, thereby enhancing metastatic behavior." (PMID 40557321, 2025). "These pro-inflammatory cytokines, such as IL-6 and TNF-α, are released by both tumor and host immune cells and initiate a cascade of intracellular signaling pathways that culminate in skeletal muscle degradation and other systemic dysregulation." (PMID 40869331, 2025). "PD-1 binds to PD-L1 to suppress T-cell activity, while IFN-γ and TNF-α in the tumor microenvironment increase PD-L1 expression, aiding tumor immune escape." (PMID 41159033, 2025). "In the tumor microenvironment, TNF-α via its receptors TNFR-I and TNFR-II plays a dual role in suppressing or promoting cancer proliferation and metastasis." (PMID 40430444, 2025). "In turn, the optical density of the reaction product for TNF-α in G3 tumor samples reached 128.02 ± 5.67% relative to G2 (p < 0.05), while in G4 samples, it increased to 171.43 ± 10.18% of G2 (p < 0.05)." (PMID 40565357, 2025). "For example, TNF-α promotes tumor cell survival, migration, and invasion, notably by activating the NF-κB signaling pathway and its downstream effectors like Snail." (PMID 41480347, 2025). "Wirkverlust sinnvoll, und valide minimale Talspiegel sind nur bei Tumor-Nekrose-Faktor(TNF)-Inhibitoren etabliert." (PMID 39747696, 2025). "This creates a vicious cycle wherein TNF-α-driven inflammation makes the tumor more aggressive and treatment-resistant." (PMID 41007766, 2025). "This was due to the fact that combined blockade resulted in higher levels of cytokines (IFN-γ, TNF-α, and granzyme B) production by tumor-specific CD8+ T cells from tumor-draining lymph nodes compared to single blockade or control group 142." (PMID 40861801, 2025). "Specifically, TNF-α plays a specific role in regulating tumor development, invasion, metastasis, acquired resistance, adaptive immune, and innate immune." (PMID 40670983, 2025). "This shift is characterized by the up-regulation of pro-inflammatory cytokines such as IL-6 and TNF-α, which have anti-tumor properties, and the down-regulation of immunosuppressive cytokines such as IL-10 and TGF-β." (PMID 40507156, 2025). "TNFRSF18 expression impaired TNF signalling, weakening T cell cytotoxicity and enabling immune escape of ribosome‐rich tumour clusters." (PMID 40770837, 2025). "By reducing the production of pro-inflammatory cytokines, such as IFN-γ and TNF-α, IL-10 diminishes the effector functions of CTLs, limiting their ability to control tumor growth." (PMID 40739089, 2025). "Inflammatory cytokines (such as tumor-associated macrophages, IL-6, VEGF, and TNF-α) can indirectly elevate HMGCR expression or activity, thereby promoting cholesterol synthesis." (PMID 41450917, 2025). "Conversely, cytotoxic T lymphocytes (CTLs), natural killer (NK) cells, and dendritic cells (DCs) release cytokines such as interferon gamma (IFN-γ) and interferon alpha (TNF-α) to identify and eliminate tumor cells, thereby inhibiting tumor growth." (PMID 39941048, 2025). "Elevated TNF (Tumor Necrosis Factor) and IL-6 (Interleukin 6) drive chronic inflammation, further promoting tumor development." (PMID 41562760, 2025). "It is worth noting that AE can decrease pro-inflammatory cytokines in the tumor microenvironment, such as TNF-α, IL-6, and CRP, by modulating immune system responses, and these cytokines play a promoting role in tumor progression." (PMID 41480347, 2025). "Our study elucidates the tumor microenvironment changes in bone invasion and identifies the critical role of TNF-α+ TAMs in promoting bone invasion of PitNETs, laying a foundation for developing new molecular markers or therapeutic agents targeting BI PitNETs." (PMID 39865310, 2025).
tumor (continued). "CD8 T cell plays an anti-tumor effect through releasing interferon-γ and TNF cytokines (Huo, Wu & Zang, 2021)." (PMID 40416605, 2025). "TNF-α was initially identified as a factor that induces tumor necrosis and was subsequently shown to act as a carcinogenic promoter in chronic inflammation." (PMID 40725854, 2025). "Remarkably, a reduction in mitochondrial Ca2+ level by chelation or Ru360 potentiates cytotoxicity induced by tumor necrosis factor (TNF)-related apoptosis-inducing ligand (TRAIL) in apoptosis-resistant tumor cells." (PMID 39866241, 2025). "We cultured the 3D model by referencing relevant literature and optimized it to “simulate the in vivo microenvironment”; for example, VEGF and TNF‐α were added to the GC organoid medium to mimic the tumor microenvironment." (PMID 41308696, 2025). "IL-1β and TNF-α play crucial roles in modulating the tumor microenvironment and promoting tumor progression." (PMID 41243973, 2025). "By contrast, M1-polarized (classically activated) macrophages produce pro-inflammatory mediators (e.g., nitric oxide via inducible nitric oxide synthase (iNOS), tumor necrosis factor (TNF)-α, IL-12) and can attack tumor cells and stimulate adaptive immunity." (PMID 41465516, 2025). "This activation leads to an increased expression of various inflammatory cytokines within the tumor microenvironment, including TNF-α, IL-6, IL-1β, and other cytokines." (PMID 40487290, 2025). "In the TME, interferon-γ (IFN-γ), interleukin-2 (IL-2), and tumor necrosis factor-α (TNF-α) play roles in anti-tumor immunity." (PMID 40183013, 2025). "In the TNF signalling communication network, we observed that high‐stemness tumour cells were less regulated by immune cells, suggesting a potential association between tumour cell stemness and immune evasion, consistent with poor RFS of RPS7, RPL8 and RPL30." (PMID 40770837, 2025). "Depletion of dietary tryptophan reduces AhR activity in TAMs, promoting the accumulation of TNF-α+IFN-γ+CD8+ T cells within the tumor and slowing tumor progression." (PMID 39905317, 2025). "Inflammatory cytokines in TME, such as IFN-ꝩ, IL-1β, IL-6, and TNF, further favorize cancer immune escape by augmenting PD-L1/PD-L2 expression on tumor cells including TNBC." (PMID 40940764, 2025). "The metastasis of tumors is facilitated by TNF-α, which exerts its influence on both the tumor cells themselves and the surrounding stromal and inflammatory cells within the tumor environment." (PMID 39941858, 2025). "The levels of immune-related factors INF-γ and TNF-α in mouse tumor tissues were assessed using ELISA." (PMID 40270974, 2025). "M1 macrophages play a central role by releasing IL-12 and TNF-α, promoting Th1 polarization and apoptotic signaling in tumor cells." (PMID 40940834, 2025). "For instance, STAT3, IL6, and TNF are key inflammatory mediators that activate downstream NF-κB signaling and support a tumor-permissive microenvironment." (PMID 40593037, 2025). "Ex vivo stimulation of PBMCs with tumor lysate or peptide pools performed approximately 4–6 weeks after ablation (relative to Day 0) can quantify the frequency and polyfunctionality (production of IFN-γ, TNF-α, IL-2) of tumor-reactive T cells." (PMID 41295487, 2025). "Currently, numerous studies have demonstrated the direct involvement of TNF-α not only in enhancing resistance to cell death but also in suppressing mitochondrial functions, including mitophagy, in tumor cells." (PMID 41463291, 2025). "TNF-α, initially identified in 1975 for its ability to induce tumor hemorrhagic necrosis, has long been recognized as a potential anticancer factor." (PMID 41325308, 2025). "This blockade promotes T-cell activation, enhances secretion of interferon (IFN)-γ and tumor necrosis factor (TNF)-α, and ultimately augments anti-tumor immunity." (PMID 40893369, 2025).